PANX2 (pannexin 2)
Description:
Ion channel with a slight anion preference. Also able to release ATP. Plays a role in regulating neurogenesis and apoptosis in keratinocytes (By similarity).
Synonyms: hPANX2; PX2
Tractability: Antibody: UniProt places it where antibodies can reach, with high confidence; its Gene Ontology location is reachable by antibodies, with high confidence; UniProt predicts a signal peptide or a membrane-spanning region; the Human Protein Atlas places it where antibodies can reach.
Gene: Protein-coding gene on chromosome 22 (50,170,731 to 50,180,295, forward strand). Ensembl gene ENSG00000073150.
Subcellular location: Cell membrane; Golgi apparatus membrane; Endoplasmic reticulum membrane
Subcellular location (Human Protein Atlas): Plasma membrane
Pathways (Reactome):
Neuronal System: Electric Transmission Across Gap Junctions
Gene Ontology:
Molecular function: gap junction hemi-channel activity; structural molecule activity; wide pore channel activity; channel activity; gap junction channel activity; protein-containing complex binding
Biological process: cell-cell signaling; monoatomic cation transport; positive regulation of interleukin-1 production; transmembrane transport
Cellular component: plasma membrane; endoplasmic reticulum membrane; Golgi membrane; cytoplasm
Genetic constraint (gnomAD): Loss-of-function variants: 28 observed, 30.01 expected, observed/expected ratio (o/e) 0.93, 90% interval 0.69 to 1.28. The synonymous counts are far from expectation, so gnomAD's model fits this gene poorly and the ratio says little. Missense variants: 861 observed, 840.69 expected, observed/expected ratio (o/e) 1.02, 90% interval 0.97 to 1.08. Synonymous variants: 532 observed, 404.07 expected, observed/expected ratio (o/e) 1.32, 90% interval 1.23 to 1.41.
Homologues: Orthologues: chimpanzee PANX2 (99% identical), dog PANX2 (92% identical), mouse Panx2 (92% identical), rat Panx2 (91% identical), pig PANX2 (91% identical), macaque PANX2 (85% identical), guinea pig PANX2 (84% identical), tropical clawed frog PANX (67% identical), zebrafish panx2 (64% identical). Paralogues in human: PANX3 (16% identical), PANX1 (16% identical).
Diseases named in the same sentence as PANX2 in open-access papers:
PANX2 is named in the same sentence as 36 diseases in open-access papers, as found by Europe PMC text mining. Sharing a sentence is not in itself a finding about the gene and the disease. The quoted sentences say what the papers report.
glioma (15 papers, 2014 to 2025). A benign or malignant brain and spinal cord tumor that arises from glial cells (astrocytes, oligodendrocytes, ependymal cells). "PANX2 is associated with the pathogenesis of prostate cancer and low-grade gliomas in the brain and can affect patient prognosis." (PMID 36465397, 2022). "Analysis of public gene expression databases reveals a positive correlation between Panx2 and post-diagnostic survival time in glioma patients; these analyses also suggest a link (albeit a much weaker one) between Panx1 and cancer in general." (PMID 24600404, 2014). "Human Panx2 DNA is located in the same chromosomal regions that are implicated in human gliomas and exogenous Panx2 transfected into rat C6 glioma cells displayed a flattened morphology and increased cell–cell contacts and significantly reduced in vitro oncogenicity parameters." (PMID 25698922, 2014). "In glioma, as well as brain low grade glioma, Panx2 expression was reduced, and its low expression predicted worse patient survival." (PMID 40909173, 2025). "The use of anti-PANX2 antibodies showed negligible or limited PANX2 expression in human glioma cells." (PMID 37241023, 2023). "Their research database showcased an increase in levels of PANX2 and correlated it with increased survival and better outcomes for glioma patients." (PMID 37241023, 2023). "These channels, including P2X, SYT16, and PANX2, have a unique impact on cell types involved in gliomas, including neurons, microglia, and astrocytes." (PMID 37241023, 2023). "Examining biomolecular changes in glioma patients has led many scientists to investigate the role of PANX2 channels in gliomas." (PMID 37241023, 2023). "For example glioma cell migration is unaffected when changing the expression of PANX2, although cell growth was directly impacted." (PMID 34975840, 2021). "Over–expressing Panx2 protein in C6 rat glioma cells reduced cell proliferation and saturation density, suppressed anchorage–independent growth and decreased in vivo tumor growth." (PMID 30862038, 2019). "Panx2, which is a member of the gap-junction protein family, showed an overall reduction in gliomas and can thus help predict post-diagnosis survival of patients with glial tumors." (PMID 26099202, 2015). "A gene array analysis showed an overall reduction of Panx2 in gliomas and a direct correlation was observed between Panx2 expression and post-diagnosis survival in patients." (PMID 25698922, 2014). "Along these lines, over-expression of Panx1 or Panx2 in rat C6 glioma cells has been shown to reduce their tumorigenicity, both in vitro and in vivo." (PMID 24600404, 2014). "Panx2 serves as tumor promotion factor in colorectal cancer and prostate cancer, while Panx2 performs anti-tumor function in glioma." (PMID 40909173, 2025). "In rat C6 glioma cells, the expression of Panx2 was significantly reduced, and restoring its expression could inhibit cell proliferation and tumor growth in vivo, indicating the tumor suppressor effect of Panx2." (PMID 40909173, 2025). "Various LGICs, including P2X, SYT16, and PANX2, have the potential to become altered in the pathogenesis of glioma, which can disrupt the homeostatic activity of neurons, microglia, and astrocytes, further exacerbating the symptoms and progression of glioma." (PMID 37241023, 2023). "However, in contrast, PANX2 decreases cell/tumor growth in C6 glioma, indicating PANX2 also plays the role of a cancer suppressor in some types of cancers." (PMID 34922551, 2021). "However, in contrast, PANX2 inhibited proliferation and tumor formation of C6 glioma cells in in vitro and in vivo." (PMID 30723706, 2019). "Pannexin 2 (PANX2), which is considered to be a target gene of miR‐423‐3p, is upregulated in glioma cells when miR‐423‐3p is inhibited, leading to a reduction in glioma cell proliferation and the induction of apoptosis." (PMID 33174687, 2020).
glioma (continued). "Such an analogy started during the last decade with the analysis of the brain cancer gene expression database REMBRANDT which revealed that the expression level of PANX2 and also PANX1 is positively correlated to post diagnosis survival of glioma patients." (PMID 29865195, 2018). "Another team of researchers reported decreased or absent levels of PANX2 mRNA in cultured human glioma cells." (PMID 37241023, 2023). "Co-localization of Panx2 and the mannose-6-phosphate receptor suggests that the endolysosome may be at least one intracellular target, although no overlap was observed between exogenous GFP tagged Panx2 and LysoTracker® or EEA1 in C6 glioma cells." (PMID 24600404, 2014).
prostate carcinoma (5 papers, 2022 to 2025). A carcinoma that arises from epithelial cells of the prostate gland. "PANX2 has been linked to upregulation of NRF2 by an undetermined mechanism in prostate cancer." (PMID 40867343, 2025). "In prostate cancer, Panx2 facilitated tumor cell proliferation, migration and invasion via ferroptosis and Nuclear Factor Erythroid 2-Related Factor 2 (NRF2) signaling pathway." (PMID 40909173, 2025). "Conversely, the CEMIP, HSPB1, and PANX2 genes, which interfere with the process of ferroptosis, can effectively promote the survival of prostate cancer cells, suggesting that ferroptosis-related genes may be prognostic biomarkers and potential drug targets for patients with prostate cancer." (PMID 38705987, 2024).
breast carcinoma (4 papers, 2021 to 2026). "In the present research, we identified 3 RNAs (hsa-miR-105-5p, BCAR1 and PANX2) might associated with prognosis and metastasis of breast cancer, which might be provide a new perspective for metastasis of breast cancer and contributed to the treatment of breast cancer." (PMID 34055638, 2021). "Panx2 expression was regulated by Orphan non-coding RNA T3p (oncRNA T3p), a powerful promoter of breast cancer metastasis, suggesting a promoting metastasis function of Panx2." (PMID 40909173, 2025). "Expression of Panx2 was significantly correlated with tumor cell migration in colorectal cancer and with metastasis in breast cancer." (PMID 40909173, 2025). "Panx2 was highly expressed in tumor tissues of colorectal cancer, bladder cancer, clear cell renal cell carcinoma (ccRCC), breast cancer, esophageal cancer, and cholangiocarcinoma, and its highly expression was significantly associated with the poor prognosis of patients." (PMID 40909173, 2025). "And Panx2, together with hsa-miR-105-5p and BCAR1, was identified as a reliable biomarker related to breast cancer metastasis." (PMID 40909173, 2025). "Inversely, breast cancer patients with higher expression level of AHRR, ANKRD52, BCAR1, PANX2, hsa-miR-105-5p, hsa-miR-4435, and LINC01742 showed the lower OS." (PMID 34055638, 2021). "The results suggested that metastasis associated RNAs, including AHRR, TTC34, CNTRL, ANKRD52, BCAR1, TMEM151B, PANX2, hsa-miR-105-5p, hsa-miR-4435, hsa-miR-5691, hsa-miR-92a-1-5p, and LINC01742 could serve as the prognostic biomarkers of breast cancer patients." (PMID 34055638, 2021).
clear cell renal cell carcinomas (3 papers, 2019 to 2022). "Although the studies of FAM83H in kidney cancer are limited, a search of the public database shows a significant association between FAM83H and pannexin-2 (PANX2) in clear cell renal cell carcinomas (CCRCCs)." (PMID 30723706, 2019). "Clinicopathologic variables and the expression of FAM83H and PANX2 in clear cell renal cell carcinomas." (PMID 30723706, 2019). "In clear cell renal cell carcinomas, the co-expression of FAM83H and pannexin-2 predicted the shortest overall survival and RFS in multivariate analysis." (PMID 35885485, 2022).
ischemia (3 papers, 2014 to 2023). A hypoperfusion of the BLOOD through an organ or tissue caused by a PATHOLOGIC CONSTRICTION or obstruction of its BLOOD VESSELS, or an absence of BLOOD CIRCULATION. "The pannexin 2 channel (PANX2) participates in multiple physiological processes including skin homeostasis, neuronal development, and ischemia-induced brain injury." (PMID 36973289, 2023). "The de novo expression of Panx2 in astroglial cells after ischemia was proposed to play a role in the neuroprotection after ischemia." (PMID 25698922, 2014).
autism (2 papers, 2012 to 2014). Persistent deficits in social interaction and communication and interaction as well as a markedly restricted repertoire of activity and interest as well as repetitive patterns of behavior. "Additionally, the data implicates individual genes SLC25A12, PANX1 and PANX2 as well as pathways previously implicated in autism." (PMID 22591576, 2012). "Two of these genes, SLC25A12 and PANX2, were also identified in a recent study of genes differentially expressed in the brains of individuals with autism compared to control brains." (PMID 22591576, 2012).
colon cancer (2 papers, 2018 to 2023). "To explore potential colon cancer risk-related genes, we compared the expression of 11 RRGs in normal and tumor tissues and found that PANX2 and GABRD are highly expressed in tumors, while PPARGC1A is less expressed in tumors." (PMID 37020539, 2023). "Moreover, we noted that some of the mRNAs (ANLN, CFL2, FJX1, HHIP, PANX2, SCN3A, VSNL1 and ZIC2) were also associated with overall survival in patients with colon cancer." (PMID 29420609, 2018).
hepatocellular carcinoma (2 papers, 2016 to 2025). A malignant tumor that arises from hepatocytes. "Panx2 has been proposed to play an important role as a tumour suppressor in brain tumours and hepatocellular carcinomas." (PMID 27229305, 2016). "Consistent with a potential role as tumour suppressor, a recent publication listed PANX2 as one of the methylated genes identified by expression profiling and DNA methylation arrays in hepatocellular carcinomas (HCC)." (PMID 27229305, 2016). "Panx2 was found to have a high degree of DNA methylation in Myelodysplastic Syndrome (MDS) and hepatocellular carcinoma (HCC)." (PMID 40909173, 2025).
kidney cancer (2 papers, 2019 to 2020). Primary or metastatic malignant neoplasm involving the kidney. "In kidney cancers, FAM83H stimulates cancer progression in cooperation with PANX2, and PANX2 has been suggested to be part of the down-stream signaling of FAM83H." (PMID 32564009, 2020).
autism spectrum disorder (1 paper, 2024). A spectrum of developmental disorders that includes autism, and Asperger syndrome. "The potential role of PANX1 in human brain development is further supported by a loss-of-function human germline PANX1 variant in a patient with severe neurological deficits, and by PANX1 and PANX2 single nucleotide polymorphisms implicated in autism spectrum disorder." (PMID 38212304, 2024).
colorectal cancer (1 paper, 2025). A primary or metastatic malignant neoplasm that affects the colon or rectum. "In colorectal cancer, the Panx2 high expression group showed a significantly higher half maximal inhibitory concentration (IC50) value for 5-Fluorouracil (5-FU), a commonly used chemotherapeutic drug for colorectal cancer." (PMID 40909173, 2025). "In colorectal cancer, Panx2 promoted tumor cell proliferation, migration, tumorigenesis and drug resistance through PI3K/AKT and epithelial-mesenchymal transition (EMT) signaling pathway." (PMID 40909173, 2025). "Suggesting treatment of Panx2 inhibitors combined with 5-FU can enhance the therapeutic effect of 5-FU single used on colorectal cancer." (PMID 40909173, 2025). "However, high Panx2 expression in testicular and colorectal cancer could help tumor cells survival and growth facing DDP or 5-FU treatment." (PMID 40909173, 2025).
epilepsy (1 paper, 2017). A brain disorder characterized by episodes of abnormally increased neuronal discharge resulting in transient episodes of sensory or motor neurological dysfunction, or psychic dysfunction. "Increasing evidence suggests that the large-pore ion channels, pannexin 1 (Panx1) and 2 (Panx2), are involved in epilepsy and brain development." (PMID 28036289, 2017). "Considering the association of epilepsy and various developmental disorders with FCD, understanding the expression pattern and cellular localization of Panx1 and Panx2 in FCD could provide constructive insights into their potential roles in the epileptogenesis and pathogenesis associated with FCD." (PMID 28036289, 2017). "Considering the ages, histories of epilepsy and seizure frequencies were similar among patients with the three types FCD, the specific expression patterns indicated a potential role of Panx2 in FCDIIb." (PMID 28036289, 2017).
Hypertension (1 paper, 2021). The presence of chronic increased pressure in the systemic arterial system. "Moreover, the abnormal expression of PANX2 was associated with the occurrence the development and progression of certain diseases, like neoplasms, multiple sclerosis, migraines, hypertension and so on." (PMID 34055638, 2021).
ischemic stroke (1 paper, 2025). A stroke disorder caused by obstruction of blood flow to the brain, due to thrombotic (local blood clot formation) or embolic (due to a blood clot or other material traveling from another site) event. "The discovery of lysophospholipids as a common stimulus for Panx1 and Panx2 may underlie the proposed compensatory roles between Panx1 and Panx2 described in ischemic stroke and insulin secretion from β-cells." (PMID 40309905, 2025).
liver diseases (1 paper, 2022). "This study is also the first to report the presence of Panx2 protein in human liver samples representing surrounding tissue of (non)neoplastic liver disease." (PMID 36381643, 2022).
neuroblastoma (1 paper, 2014). Neuroblastoma (NB) is the most common solid, extracranial childhood tumor. "Intriguingly, Panx2 has been shown to co-localize with the endolysosomal enriched mannose-6-phosphate receptor in N2a neuroblastoma cells expressing Panx2 tagged with GFP." (PMID 25505382, 2014).
sensorineural hearing loss (1 paper, 2025). "Furthermore, immune infiltration analysis reveals significant correlations between FRGs (e.g., MEF2C with NK cells, PANX2 with M1 macrophages) and pro-inflammatory subsets, suggesting that ferroptosis may amplify cochlear inflammation—a known driver of sensorineural hearing loss." (PMID 40353062, 2025).
Stroke (1 paper, 2018). Sudden impairment of blood flow to a part of the brain due to occlusion or rupture of an artery to the brain. "Other potential routes of ATP release that are involved in stroke-induced neurodegeneration implicated Cx43 hemichannels or Panx2 channels; however, these channels are not blocked by trovafloxacin." (PMID 29439712, 2018).